IFNGR2 (interferon gamma receptor 2)
Description:
Associates with IFNGR1 to form a receptor for the cytokine interferon gamma (IFNG). Ligand binding stimulates activation of the JAK/STAT signaling pathway. Required for signal transduction in contrast to other receptor subunit responsible for ligand binding.
Synonyms: AF-1; IFNGT1; IFGR2; IMD28
Tractability: Small molecule: a structure with a bound ligand is known. Antibody: UniProt places it where antibodies can reach, with high confidence; its Gene Ontology location is reachable by antibodies, with high confidence; UniProt predicts a signal peptide or a membrane-spanning region. PROTAC: ubiquitination databases record sites on it. Other modalities: an approved drug acts on it.
Gene: Protein-coding gene on chromosome 21 (33,403,369 to 33,479,348, forward strand). Ensembl gene ENSG00000159128.
Subcellular location: Cell membrane; Cytoplasmic vesicle membrane; Golgi apparatus membrane; Endoplasmic reticulum membrane; Cytoplasm
Subcellular location (Human Protein Atlas): Golgi apparatus; Nucleoplasm
Pathways (Reactome):
Immune System: IFNG signaling activates MAPKs; Interferon gamma signaling; Regulation of IFNG signaling
Disease: Potential therapeutics for SARS
Gene Ontology:
Molecular function: protein binding; type II interferon receptor activity; cytokine receptor activity
Biological process: type III interferon-mediated signaling pathway; cell surface receptor signaling pathway; cellular response to virus; cytokine-mediated signaling pathway; response to virus; type II interferon-mediated signaling pathway; microglial cell activation
Cellular component: endoplasmic reticulum; plasma membrane; cytoplasm; cytoplasmic vesicle membrane; endoplasmic reticulum membrane; Golgi membrane
Genetic constraint (gnomAD): Loss-of-function variants: 15 observed, 37.85 expected, observed/expected ratio (o/e) 0.4, 90% interval 0.26 to 0.61. The upper end of that interval is the gene's LOEUF score, 0.61, which puts it in group 2 of 6, group 1 being the genes least tolerant of losing a copy. Missense variants: 362 observed, 420.56 expected, observed/expected ratio (o/e) 0.86, 90% interval 0.79 to 0.94. Synonymous variants: 161 observed, 169.38 expected, observed/expected ratio (o/e) 0.95, 90% interval 0.83 to 1.08.
Homologues: Orthologues: chimpanzee IFNGR2 (98% identical), macaque IFNGR2 (94% identical), dog IFNGR2 (70% identical), rabbit IFNGR2 (68% identical), pig IFNGR2 (66% identical), guinea pig IFNGR2 (62% identical), rat Ifngr2 (59% identical), mouse Ifngr2 (59% identical), tropical clawed frog ifngr2 (28% identical), tropical clawed frog ifngr2.2 (28% identical). Paralogues in human: IL10RB (20% identical), IL20RB (19% identical), IL20RA (17% identical), IFNAR1 (16% identical), IFNAR2 (15% identical), IFNGR1 (15% identical), IL10RA (15% identical), F3 (14% identical), IFNLR1 (14% identical), IL22RA1 (13% identical), IL22RA2 (12% identical).
Diseases named in the same sentence as IFNGR2 in open-access papers:
IFNGR2 is named in the same sentence as 88 diseases in open-access papers, as found by Europe PMC text mining. Sharing a sentence is not in itself a finding about the gene and the disease. The quoted sentences say what the papers report.
glioma (12 papers, 2019 to 2026). A benign or malignant brain and spinal cord tumor that arises from glial cells (astrocytes, oligodendrocytes, ependymal cells). "Similarly, IFNGR2 has been implicated in glioma prognosis and responsiveness to immune checkpoint blockade." (PMID 40842996, 2025). "IFNGR2, the receptor for interferon-gamma, plays a dual role in immune response modulation and is associated with the polarization of microglia and macrophages within the glioma microenvironment, influencing immunogenicity and the efficacy of immunotherapies." (PMID 38137116, 2023). "In addition, GO analysis corroborates the pro-inflammatory microenvironment of the IFNGR score-high group, suggesting that the upregulation of IFNGR1 and IFNGR2 was associated with enhanced inflammatory and immune response in gliomas." (PMID 35492352, 2022). "Similarly, IFNGR2 has been linked to glioma prognosis and response to immune checkpoint blockade." (PMID 40842996, 2025). "IFNGR2 was predominantly expressed in monocytes, M1 macrophages, and MES-like malignant cells, aligning with previous findings that IFNGR2 is preferentially expressed by monocyte/macrophage populations within the glioma microenvironment." (PMID 40842996, 2025). "Given the important roles of TGFB ligands and IFN-γ released by immune cells in the TME as related to IDH mutational status, we tested the clinical prognostic significance of high tumor TGFB2 and IFNGR2 mRNA levels measured in low-grade gliomas." (PMID 38539537, 2024). "We also found that RUNX1 can regulate the transcription and expression of IFNGR2 and is involved in the regulation of glioma cell proliferation, cycle, apoptosis, invasion, and migration, and the differentiation process of glioma mutant subtypes." (PMID 36321611, 2023). "IFNGR1 and IFNGR2 were used as concise IFNG-related gene signature based on which the IFNGR score well-characterized the IFNG response in the glioma microenvironment." (PMID 35492352, 2022). "Due to the profound impact on survival in glioma patients, 4 genes, namely IFNGR2, GLUD1, PPIA, and CASP8 were identified." (PMID 36466844, 2022). "Subsequent results confirmed that RUNX1, as an independent prognostic factor for LGG, may target interferon-gamma receptor 2 (IFNGR2) to regulate glioma cell proliferation, invasion, and migration." (PMID 36321611, 2023). "In the intricate landscape of glioma pathogenesis, the elucidation of risk scores derived from pivotal hub genes—RPL3, RPL12, PTEN, IFNGR2, KLF10, PLAUR, MSN, and IKBIP—emerged as a critical component in understanding the disease’s progression and patient stratification." (PMID 38137116, 2023). "Further cell experiments revealed that RUNX1 could regulate the transcription and expression of IFNGR2 as well as participate in glioma cell proliferation, cycle, apoptosis, invasion, and migration, which may be realized through the IL2-STAT5 pathway." (PMID 36321611, 2023). "To our knowledge, we have for the first time explored the role of IFNGR1 and IFNGR2 in gliomas." (PMID 35492352, 2022). "Notably, IFNGR1 and IFNGR2 were preferentially expressed by the Mono/Macro cells in the glioma microenvironment and were significantly correlated with M2 macrophage." (PMID 35492352, 2022). "Therefore, IFNGR1 and IFNGR2 may also constitute a genetic metric of clinical implications in glioma." (PMID 35492352, 2022). "In this study, we have developed a concise IFNG-related gene signature to characterize the prognosis of gliomas based on the expression of IFNGR1 and IFNGR2." (PMID 35492352, 2022). "Both IFNGR2 and CASP8 represented the common intersection genes as revealed by the venn plot after combining the DEGs between glioma and normal brain tissues, NRS gene set, and important survival genes from the random forest." (PMID 36466844, 2022). "Other downregulated genes include an interferon-γ receptor IFNGR2, integrin subunits ITGA/B, and PDGFC, which can de-differentiate astrocytes in glioma cell lines." (PMID 31231645, 2019).
glioma (continued). "Additionally, patients with low-grade gliomas with high expression levels of RUNX1 and/or IFNGR2 have a worse prognosis, with a significant increase in the infiltration of M2 macrophages." (PMID 38430423, 2024). "Among them, IFNGR2, TXLNA, PSMC2, and TMSB15A have not been reported to be associated with gliomas." (PMID 37867596, 2023). "Although various IFNG-related inflammatory responses may be active in the glioma microenvironment with elevated IFNGR scores, macrophages with increased expression of IFNGR1 and IFNGR2 were preferentially subject to transcriptional regulation by NF-κB and STAT3." (PMID 35492352, 2022).
melanoma (10 papers, 2017 to 2025). A malignant, usually aggressive tumor composed of atypical, neoplastic melanocytes. "Here, the authors show that loss of IFNGR2 or JAK1 in a melanoma cell line enhances T cell mediated lysis, however these cells are paradoxically more sensitive to immune-mediated tumor control in vivo due to the loss of PD-L1." (PMID 32001684, 2020). "IFNGR2, a critical subunit of the interferon‐gamma receptor, is known to enhance immune responses and improve immunotherapy efficacy in melanoma and other tumors." (PMID 40977852, 2025). "Since the IFN-γ signaling pathway in melanoma cells induces tumor growth arrest and death, mutations of IFNGR1, IFNGR2, JAK1, JAK2, STAT1, and IRF3 lead to insensitivity to anti-tumor IFN-γ activity." (PMID 35432377, 2022). "Ex vivo exposure to IL‐12 has been shown to protect tumor‐infiltrating murine CD8+ T cells from negative regulation by IFN‐γ via downregulation of IFNγR2 and PD‐1 expression in a mouse model of melanoma." (PMID 33552509, 2021). "Here using a genome-wide CRISPR screen in B16.SIY melanoma cells, we confirm Ifngr2 and Jak1 as important genes conferring sensitivity to T cell-mediated killing in vitro." (PMID 32001684, 2020). "Whole-exome sequencing of human melanoma tissues and the human melanoma cell line revealed that acquired resistance can result from loss-of-function mutations of IFNGR1, IFNGR2, JAK1, JAK2, STAT1, and IRF3 from the IFN-γ signaling pathway and β2M from antigen presentation pathway." (PMID 35432377, 2022). "Our ligand-receptor-based cell communication analysis demonstrated increased interactions between ETV4-low melanoma cells and T cells, including TNFSF14-LTBR and IFNG-(IFNGR1+IFNGR2) signaling pathways." (PMID 41502516, 2025). "The immunohistochemical images of IFNGR2, CCL25, IL15, RTP4, and NLRP6 in both normal skin tissue and melanoma tissue confirmed the expression of the GRIPs in CM." (PMID 35492358, 2022).
COVID-19 (9 papers, 2021 to 2025). A disease caused by infection with severe acute respiratory syndrome coronavirus 2. "IFN genes IFNG and IFNE, and IFN receptors IFNAR2 and IFNGR2, were upregulated in COVID-19 vs non-COVID19, suggesting a crucial role for IFN-signaling in mounting an anti-SARS-Cov-2 response." (PMID 33473155, 2021). "We also found that the elevated pro-inflammatory cytokines (IFNGR1, IFNGR2, and TGFB2) were significantly co-expressed with ACE2 in male squamous cells from critically ill COVID-19 patients." (PMID 34330889, 2021). "The top molecules in the COVID-19 T1 and T2 data set with the greatest alteration in methylation compared to healthy controls included hypomethylated MUC20, VAV3, CCL20, and mir21 and hypermethylated GIT2, IFNGR2, FCER1G, and OLR1." (PMID 41227320, 2025). "In CD14+ monocytes, HIF-1 signaling may regulate LDHA, ALDOA, TIMP1, ELOB and IFNGR2, and PPAR signaling may regulate UBC, RXRA, DBI and ACSL1 in COVID-19 patients." (PMID 33936072, 2021). "Additionally, in situ hybridization staining across patients and 138 ROIs also highlighted significantly higher numbers of IFNGR2+ cells in patients with COVID-19 than in non-LRTD controls but not between non-LRTD patients and patients with LRTD." (PMID 39567718, 2024). "In module 2, enhanced expression of glycolysis (GAPDH and TPI1) and IFN response (IFITM2, IFITM1, IFITM3, IFNGR2, and ISG20) genes in human COVID-19 patients, particularly severely ill patients, may promote the differentiation of unswitched memory B cells into plasmablasts." (PMID 33936072, 2021).
psoriasis (5 papers, 2015 to 2025). An autoimmune condition characterized by red, well-delineated plaques with silvery scales that are usually on the extensor surfaces and scalp. "IFNGR2 has been identified as a potential causal gene for two immune-related diseases: rheumatoid arthritis and psoriasis." (PMID 35204186, 2022). "This study emphasized the role of up‐regulated circ_0003738 in attenuating the suppressive effect of psoriatic Tregs by sponging miR‐562/IL17RA and miR‐490‐5p/IFNGR2 axes, revealing possible novel therapeutic targets for psoriasis treating." (PMID 39873909, 2025).
rheumatoid arthritis (4 papers, 2017 to 2023). A chronic, systemic autoimmune disorder characterized by inflammation in the synovial membranes and articular surfaces. "In Mendelian randomization, the expression of IFNGR2 (beta=− 0.12, SE=0.02, PIVW= 7.78E − 12) and IFNAR2 (beta=− 0.08, SE=0.03, PIVW=0.004) in blood cells were negatively associated with the risk of rheumatoid arthritis." (PMID 37019979, 2023). "IFNGR2 has not been shown to participate in the IDD process, but it has been found in rheumatoid arthritis." (PMID 36081453, 2022).
glioblastoma (3 papers, 2013 to 2022). The most malignant astrocytic tumor (WHO grade IV). "Of these, only ATF6 and IFNGR2 have been previously associated with glioblastoma viability and treatment resistance, while the remaining three have only been identified in other cancer types, which encourages further investigations." (PMID 36497269, 2022). "In terms of interferons and receptors, IFNGR2 conferred sensitivity to T-cell mediated cytotoxic activity and enhanced the anti-tumor effectiveness of CD8+ T cells in vitro, while high expression of IFNB1 was associated with chemotherapy resistance and a poor prognosis in glioblastoma." (PMID 35145511, 2021). "Fn14 was found to be co-expressed with IGFBP2 and 3 and VEGFA, IFNγR2, TNFR1A and IGFBP2 and lamin A, suggesting a possible role of this receptor in glioblastoma angiogenesis." (PMID 24376672, 2013).
Insulin resistance (3 papers, 2015 to 2024). Increased resistance towards insulin, that is, diminished effectiveness of insulin in reducing blood glucose levels. "Obesity-mediated liver inflammation is also attenuated in Lyz-IFNγR2−/− mice with profoundly reduced intrahepatic levels of IL-12, and in vivo treatment with IL-12 causes insulin resistance by impairing hepatic insulin signaling in wild-type (WT) mice." (PMID 38951527, 2024). "We demonstrate that Lyz-IFNγR2−/− mice are protected from diet-induced insulin resistance despite developing fatty liver, and this is associated with improved insulin signaling in the liver." (PMID 38951527, 2024). "Here, we show that male mice with loss of IFNγ signaling in myeloid cells (Lyz-IFNγR2−/−) are protected from diet-induced insulin resistance despite fatty liver." (PMID 38951527, 2024). "A chronic IL-12 treatment re-establishes hepatic insulin resistance and inflammation in Lyz-IFNγR2−/− mice." (PMID 38951527, 2024). "Our data demonstrated significant increases in the expression levels of several lipid metabolism-related genes, including IFNGR2 and NFX1, which modulate lipid metabolism to promote insulin resistance." (PMID 26089598, 2015). "Nevertheless, IFNGR2 is part of the interferon-γ receptor complex involved in the JAK (Janus kinase)/STAT (signal transducer and activator of transcription) signalling pathway, which may contribute to adipocyte dysfunction and insulin resistance, the latter possibly occurring in our Fat line." (PMID 36414820, 2023).
liver fibrosis (3 papers, 2015 to 2024). "Following MASH diets, Lyz-IFNγR2−/− mice are rescued from developing liver fibrosis, which is associated with reduced fibroblast growth factor (FGF) 21 levels." (PMID 38951527, 2024). "Following MASH diets, Lyz-IFNγR2−/− mice are rescued from developing liver fibrosis, which is associated with increased hepatic expression of forkhead box protein O1 (FoxO1) and reduced fibroblast growth factor (FGF) 21 levels." (PMID 38951527, 2024).
Primary Immunodeficiency (3 papers, 2015 to 2022). "Discrete alterations in glycan expression due to mutations in immune molecules (e.g., IFNGR2) have also been shown to result in primary immunodeficiency." (PMID 26125015, 2015).
tuberculosis (3 papers, 2015 to 2025). A chronic, recurrent infection caused by the bacterium Mycobacterium tuberculosis. "Over the years, several studies have identified genetic polymorphisms associated with different molecules in the IFN-γ induction pathway, especially T-Bet, STAT1, and IFNGR1/IFNGR2, and these polymorphisms seem to influence susceptibility to several infectious diseases, including tuberculosis." (PMID 26000298, 2015). "The “MAPK Signaling Pathway” includes genes like MAP3K2, PLA2G4A, and NFKB1, Lastly, the “Tuberculosis” pathway involves IFNGR2, ITGB2, and IL12B." (PMID 40621499, 2025).
viral infection (3 papers, 2021 to 2026). "Missense mutations were identified in the IFN-α receptors 1 and 2 (IFNAR1 and IFNAR2), the IFNGR2, the IFNLR1, receptors critical for the response to viral infections." (PMID 41522351, 2026). "There was an elevated expression of IFNAR1 (IFNα/β receptor subunit 1), IFNAR2 (IFNα/β receptor subunit 2), IFNGR1 (IFNγ receptor subunit 1) and IFNGR2 (IFNγ receptor subunit 2) in MIS-C, bacterial infection and KD in comparison with viral infection." (PMID 39300098, 2024).
Alzheimer disease (2 papers, 2022 to 2025). A progressive, neurodegenerative disease characterized by loss of function and death of nerve cells in several areas of the brain leading to loss of cognitive function such as memory and language. "In Alzheimer’s disease, IFN-γ couples with choroidal–cerebral neuroimmune interactions, and a variety of IFN signaling-related genes, including IFNGR2, are up-regulated, suggesting that IFNGR2 may be involved in the pathogenesis." (PMID 35204186, 2022).
asthma (2 papers, 2016 to 2024). "Our results included genes and CpGs implicated in previous studies of obstructive lung disease and exacerbations, including GRASP and IFNGR2 (previous genetic associations with asthma) as well as FYXD1 (differential methylation associated with response to systemic steroids and COPD)." (PMID 27814717, 2016). "The role of IFNγR2 and more in general of Th1 cytokines in asthma appears complex." (PMID 39202464, 2024).
colorectal cancer (2 papers, 2020 to 2023). A primary or metastatic malignant neoplasm that affects the colon or rectum. "Thus, it is worth to verify experimentally whether the IFNγ/IFNGR2/APC/TCF4/GPX4 axis exists in colorectal cancer cells that, once taking on actions, triggers ferroptosis in colorectal CSCs." (PMID 37671945, 2023).
Down syndrome (2 papers, 2021 to 2024). "For example, four IFN receptor genes (IFNAR1, IFNAR2, IFNGR2, and IL10RB) and two IFN-stimulated genes (MX1 and MX2) are triplicated in Down syndrome, and individuals with Down syndrome exhibit hypersensitivity to type I IFN (IFN-I)." (PMID 38540156, 2024).
immunodeficiencies (2 papers, 2017 to 2024). "IFNGR2 has been previously implicated in various immunodeficiencies." (PMID 28384278, 2017).
lung carcinoma (2 papers, 2021 to 2025). "IFNGR1 and IFNGR2, the cognate receptors of IFNG, were expressed in both monocytes in blood and macrophages in lung cancer." (PMID 35069521, 2021).
metastatic melanoma (2 papers, 2017 to 2023). A melanoma that has spread from its primary site to another anatomic site. "We report that expression of the IFNγ receptor β chain (IFNγR2) in CD8 T cells negatively correlates with clinical responsiveness to checkpoint blockade in metastatic melanoma patients, suggesting that the loss of sensitivity to IFNγ contributes to successful antitumor immunity." (PMID 36658158, 2023).
Obesity (2 papers, 2022 to 2023). Accumulation of substantial excess body fat. "It is possible that differential expression of Ifngr2 and Lat contributes to the chronic, low-grade inflammation of adipose tissue that has been reported previously and links obesity to type II diabetes." (PMID 36414820, 2023).
ovarian carcinoma (2 papers, 2020 to 2023). A malignant neoplasm originating from the surface ovarian epithelium. "For example, CAF-derived exosomes deliver circ-IFNGR2 to ovarian cancer cells and inhibit malignant tumor progression by regulating the microRNA-378/ST5 axis." (PMID 37525158, 2023).